EIF2A (eukaryotic translation initiation factor 2A)
Diseases named in the same sentence as EIF2A in open-access papers (continued):
Sharing a sentence is not in itself a finding about the gene and the disease.
infection (21 papers, 2011 to 2026). The state of being infected such as from the introduction of a foreign agent such as serum, vaccine, antigenic substance or organism. "The loss of eIF2A or eIF2D essentially prevents replication of PV requiring a longer infection time." (PMID 36689548, 2023). "This form of unconventional translation is enhanced by cellular stress caused by tumorigenesis, infection or nutrient starvation via phosphorylation of eIF2α and formation of an alternative ternary complex composed of eIF2A‐GTP, which replaces eIF2‐GTP." (PMID 34310018, 2021). "In the presence of eIF2A and eIF2D, PV establishes infection faster, replicates to higher levels, and replicates faster than in the absence of one of these factors." (PMID 36689548, 2023). "This tool permitted us to compare outcomes for transfection or infection in the absence or presence of eIF2A or eIF2D." (PMID 36689548, 2023). "The phosphorylation profiles of pJNK/JNK, p-eIF2a/eIF2a, and pNF-κB/NF-κB were elevated after WT and ΔespF/pespF infection." (PMID 35847082, 2022). "In the context of vaccinia virus infection, an N-terminally truncated E3L gene resulted in altered eIF2α phosphorylation levels at 6 h, but led to increased eIF2a phosphorylation at 9 and 12 h after infection." (PMID 35891544, 2022). "Our study will be also useful for investigating how other rotavirus proteins or infection-induced physiological changes (e.g., stress and eIF2a phosphorylation) impact rotavirus gene expression." (PMID 26727111, 2016). "Upon infection, the expression of EIF2A, EIF3D, EIF4G1, and EIF4A was increased." (PMID 38674742, 2024). "While population-level studies only revealed a role for eIF2A and eIF2D when in vitro transcribed RNA was transfected into cells to initiate infection and/or recombination, studies at the single-cell level suggested a role for these factors during normal, virus-initiated infection." (PMID 36689548, 2023). "Similarly, infection with ZIKV inhibited arsenite-induced SG formation by preventing phosphorylation of EIF2A." (PMID 34452345, 2021). "Furthermore, infection with the Usutu virus, a member of the genus Flavivirus, also inhibited arsenite-induced EIF2A phosphorylation and SG formation." (PMID 34452345, 2021). "It has also been proposed that eIF2A could act as a substitute for eIF2 in infections with Sindbis virus." (PMID 21779397, 2011). "We focused specifically on the activation of the ISR kinases PERK and PKR, the downstream effects on p-eIF2a, and the role of GADD34 and CReP during infection." (PMID 39861909, 2025). "Infection with VACVΔE3 resulted in the phosphorylation of both PKR and eIF2a, however the defect of VACVΔE3 can be rescued in PKR-deficient HeLa cells." (PMID 23853588, 2013). "Of the genes, K1L and C7L prevent eIF2a phosphorylation to inhibit cellular and viral protein synthesis in modified VACV Ankara (MVA) infection." (PMID 22363781, 2012). "Although we observed PKR phosphorylation during NL63 infection of all three cell types and during 229E infection of nasal cell cultures, we did not consistently observe phosphorylation of its downstream mediator, eIF2a." (PMID 41369222, 2026). "In contrast, introduction of the nanoLuc reporter by infection did not exhibit a significant dependence of either eIF2A or eIF2D." (PMID 36689548, 2023). "We conclude that the IRES-independent, eIF2A/eIF2D-dependent mechanism likely functions during normal infection when certain factors are present or not in the host cell." (PMID 36689548, 2023). "We did not observe a strong dependence on eIF2A and/or eIF2D when infection was launched using virus." (PMID 36689548, 2023). "First, infections that required longer than 5 hours for completion appeared to be lost in the absence of eIF2A or eIF2D." (PMID 36689548, 2023). "Infection of 293/ACE2 cells with SARS-CoV-1 lead to activation of PKR followed by phosphorylation of and hence inactivation of the translation initiation factor EIF2A." (PMID 33806254, 2021).
infection (continued). "Second, 25% of the cells appeared recalcitrant to infection in the absence of eIF2A or eIF2D." (PMID 36689548, 2023). "One-quarter of cells exposed to PV do not establish infection in the absence of eIF2A or eIF2D." (PMID 36689548, 2023). "Moreover, silencing of eIF2A or eIF2D by transfection of the corresponding siRNAs in HAP1 WT, HAP1-eIF2A− and HAP1-eIF2D− cells had little effect on the synthesis of viral proteins late in infection." (PMID 28240315, 2017). "Another study showed that P58IPK regulates the eukaryotic translation initiation factor eIF2a, and then regulates IAV mRNA translation and infection through a PKR-mediated mechanism, which is independent of PERK." (PMID 30966844, 2019). "Given that genes containing an uORF are preferentially translated in the presence of phosphorylated EIF2A, we propose that the integrated stress response is not directing posttranscriptional restriction in SARS-CoV-2 infected Calu-3 cells at 24 h post infection." (PMID 33806254, 2021).
neurodegenerative disease (2 papers, 2018 to 2020). A disorder of the central nervous system characterized by gradual and progressive loss of neural tissue and neurologic function. "The other five genes, bound by Tau under HS conditions (as also Grm5), were chosen according to their implication in neurodegenerative diseases (Trex1, Dlg2, Dlg1, Xrcc6, Eif2a)." (PMID 30321409, 2018).
EIF2A also shares sentences with these, for which no sentence is quoted: Hyperglycemia (2 papers); Obesity (2); preeclampsia (2); acute lymphoblastic leukemia (1); airway allergy (1); brain injury (1); cognitive deficits (1); congenital cataracts (1); COVID-19 (1); deafness (1); diabetes (1); esophageal cancer (1); esophageal squamous cell carcinoma (1); gastric cancer (1); glioblastoma (1); glomerulosclerosis (1); hypertensive disorders of (1); Hypoglycemia (1); hypothyroidism (1); immune dysfunction (1); Insulin resistance (1); kidney disease (1); liposarcoma (1); lupus (1); multiple myeloma (1); myopia (1); myotonic dystrophy type 2 (1); pleural mesothelioma (1); pregnancy disorder (1); retinal degeneration (1).
A further 3 diseases each share a sentence with EIF2A in 1 paper.